EPPIN (epididymal peptidase inhibitor)
Description:
Serine protease inhibitor that plays an essential role in male reproduction and fertility. Modulates the hydrolysis of SEMG1 by KLK3/PSA (a serine protease), provides antimicrobial protection for spermatozoa in the ejaculate coagulum, and binds SEMG1 thereby inhibiting sperm motility.
Synonyms: CT71; SPINLW1; WAP7; WFDC7; EPPIN1; EPPIN2; EPPIN3; dJ461P17.2; CT72
Tractability: Antibody: UniProt places it where antibodies can reach, with medium confidence; UniProt predicts a signal peptide or a membrane-spanning region; its Gene Ontology location is reachable by antibodies, with medium confidence.
Gene: Protein-coding gene on chromosome 20 (45,540,626 to 45,547,752, reverse strand). Ensembl gene ENSG00000101448.
Subcellular location: Secreted (Isoform 1); Cell surface
Pathways (Reactome):
Immune System: Antimicrobial peptides
Gene Ontology:
Molecular function: protein binding; peptidase inhibitor activity; serine-type endopeptidase inhibitor activity
Biological process: defense response to bacterium; negative regulation of calcium ion import; negative regulation of flagellated sperm motility; negative regulation of peptidase activity
Cellular component: cell surface; extracellular region; protein-containing complex; sperm plasma membrane; acrosomal vesicle; cytoplasm; sperm flagellum; sperm head
Genetic constraint (gnomAD): Loss-of-function variants: 10 observed, 12.6 expected, observed/expected ratio (o/e) 0.79, 90% interval 0.49 to 1.35. The upper end of that interval is the gene's LOEUF score, 1.35, which puts it in group 5 of 6, group 1 being the genes least tolerant of losing a copy. Missense variants: 91 observed, 108.7 expected, observed/expected ratio (o/e) 0.84, 90% interval 0.71 to 1. Synonymous variants: 42 observed, 41.83 expected, observed/expected ratio (o/e) 1, 90% interval 0.78 to 1.3.
Homologues: Orthologues: chimpanzee EPPIN (98% identical), macaque SPINLW1 (89% identical), pig EPPIN (65% identical), rat Eppin (62% identical), mouse Eppin (62% identical), guinea pig EPPIN (58% identical), zebrafish spint1b (31% identical), zebrafish spint1a (26% identical), Caenorhabditis elegans Y43F8B.3 (25% identical), Caenorhabditis elegans T21D12.7 (24% identical), zebrafish wfikkn1 (23% identical), Caenorhabditis elegans C54D10.10 (20% identical), and 8 more. Paralogues in human: WFIKKN1 (33% identical), WFIKKN2 (33% identical), WFDC6 (30% identical), TFPI (28% identical), AMBP (27% identical), SPINT1 (26% identical), SPINT2 (23% identical), TFPI2 (23% identical), WFDC8 (20% identical), KIAA0319L (17% identical), SPINT4 (16% identical), KIAA0319 (14% identical), and 1 more.
Diseases named in the same sentence as EPPIN in open-access papers:
EPPIN is named in the same sentence as 3 diseases in open-access papers, as found by Europe PMC text mining. Sharing a sentence is not in itself a finding about the gene and the disease. The quoted sentences say what the papers report.
infertile (1 paper, 2018). "Genetic polymorphisms of EPPIN have recently been reported, some associated with infertility." (PMID 30410765, 2018). "Several male monkeys (5 out of 9) that showed a high titer of anti-EPPIN antibody after immunization were found infertile clearly suggesting that EPPIN is an important protein for reproductive function." (PMID 30410765, 2018).
male infertility (1 paper, 2020). The inability of the male to effect fertilization of an ovum after a specified period of unprotected intercourse. "Genetic variants of the EPPIN are also reported to be associated with idiopathic male infertility." (PMID 32529252, 2020). "Briefly, a study in Macaca radiata monkeys immunized with recombinant human EPPIN showed an effective and reversible male infertility without hormone disruption." (PMID 32529252, 2020).
EPPIN also shares sentences with these, for which no sentence is quoted: hypothyroidism (1 paper).